CCR6 (C-C motif chemokine receptor 6)
Diseases named in the same sentence as CCR6 in open-access papers (continued):
Sharing a sentence is not in itself a finding about the gene and the disease.
emphysema (4 papers, 2013 to 2025). "DCs, CCR6, and the severity of emphysema were significantly increased in the COPD group than in controls (all P values <0.001), and they were significantly reduced after anti-CCL20 treatment compared with the COPD group (all P values <0.05)." (PMID 27586551, 2016). "In a side stream exposure study, the effect of CCR5 knockout was only protective to 25%, whereas CCR6 knockout was more effective with 67% protection against emphysema." (PMID 23720629, 2013). "The CCR6/CCL20 complex is one of the most potent regulators of dendritic cell migration to the lung and CCR6 knockout mice may be partially protected against cigarette smoke-induced emphysema due to reduced recruitment of inflammatory cells to the lung." (PMID 25306249, 2014).
endometriosis (4 papers, 2021 to 2023). The growth of functional endometrial tissue in anatomic sites outside the uterine body. "Our team has previously discovered that the CCL20/CCR6 signaling axis mediated by macrophages can promote the proliferation and migration of ESCs by blocking autophagic flux in endometriosis." (PMID 37816731, 2023). "Since the mechanism by which macrophage-involved immune dysfunction contributes to endometriosis progression is imperfect, investigations of the CCL20/CCR6 axis in endometriosis are of interest." (PMID 35841069, 2022). "The in vivo suppressive effect of CCL20/CCR6 axis inhibitors on endometriosis lesions was also demonstrated in mice models." (PMID 35841069, 2022). "In this study, we demonstrated for the first time that macrophages facilitated endometriosis progression via the CCL20/CCR6 axis." (PMID 35841069, 2022). "Recently, some studies have explored the role of the CCL20/CCR6 axis in immunological interactions in endometriosis and examined its existence in ectopic tissues." (PMID 35841069, 2022). "Th17 cells express CCR6 (C-C Motif Chemokine Receptor 6), a receptor for the CCL20 (C-C Motif Chemokine Ligand 20) ligand that is produced by endometriosis stromal cells and has a chemotactic effect on Th17 cells." (PMID 37446108, 2023). "Interestingly, CCR6 is also expressed by Th17 cells and, indeed, CCL20 may also play a role in chemotaxis and activation of these cells in the course of endometriosis." (PMID 34501240, 2021).
Hepatitis (4 papers, 2015 to 2023). Inflammation of the liver. "Our findings are in accordance with these previous studies by showing an association between CCR6-dependent inflammatory recruitment and the progression of liver inflammation and fibrosis." (PMID 26691857, 2015). "The accumulation of γδ T cells in the liver in CCL4-induced hepatitis has been reported to be CCR6-dependent." (PMID 37475963, 2023).
leprosy (4 papers, 2013 to 2025). Leprosy is a chronic infectious disease affecting primarily the skin and peripheral nervous system. "Contacts of patients with leprosy are mainly associated with CXCR3/CCR4/HLA-DR and LL/BL patients with %B-06 (IgD+) and CCR6/CCR7." (PMID 40683203, 2025). "We further investigated the requirement for phosphorylation of STAT3 in CCR6+ IL-17A+ cells using flowcytometry in 3 of each leprosy patients." (PMID 27035913, 2016). "In conformity with our earlier reports antigen stimulated PBMC of both types of leprosy reactions also showed IL-17 to be present in CD4+CCR6+ cells, along with the signature transcription factor RORC and pSTAT3." (PMID 27035913, 2016). "The HS3ST2 gene was consistently more expressed in MB leprosy lesions compared to PB, whereas the opposite was observed for CD40LG and CCR6." (PMID 34695167, 2021).
Psoriasiform dermatitis (4 papers, 2018 to 2023). A skin abnormality characterized by redness and irritation, with thick, red skin that displays flaky, silver-white patches (scales). "Inhibition of the CCL20/CCR6 axis attenuated experimentally induced psoriasiform dermatitis." (PMID 37049538, 2023).
Salmonella Infections (4 papers, 2010 to 2021). Infections with bacteria of the genus SALMONELLA. "In addition, CCR6+ DCs are rapidly recruited within the follicle-associated epithelium of the SI Peyer's Patches after oral Salmonella infection." (PMID 20399121, 2010). "We found that S. Infantis induces an increase in the proportion of proinflammatory CD4+ IFNγ+ T cells in Peyer’s patches in pigs; however, little is known regarding the roles of CD4+/− CCR6+/− T cells or CCR6+/− IFNγ+/− T cells during Salmonella infection." (PMID 32093767, 2020). "However, the precise roles played by CD4+/− CCR6+ T cells and their cytokines in response to Salmonella infection remain to be elucidated." (PMID 32093767, 2020). "To examine the role of CCR6+ T cells in reponse to Salmonella infection, we investigated the percentage of CD4+/− CCR6+/− T cells in peripheral blood at 0, 24, and 192 h following S. Infantis challenge." (PMID 32093767, 2020). "We characterized the activation and memory state of SFB-induced IL-17A and/or IL-22 producing CD4+ T cells based on the expression of specific markers including CCR6, CD44, and CD62L in the presence or absence of Salmonella infection." (PMID 34566952, 2021).
Stroke (4 papers, 2018 to 2022). Sudden impairment of blood flow to a part of the brain due to occlusion or rupture of an artery to the brain. "CCR6 has been implicated in several diseases, including spinal cord injury, traumatic brain injury, and stroke, and is upregulated by cytokines during neurodegeneration." (PMID 35453602, 2022). "In a model of experimental stroke, genetic deficiency in Ccr6 was associated with diminished infiltration of natural IL-17 releasing γδ T cells and a significantly improved neurological outcome, outlining the role CCR6 plays in pro-inflammatory immune cell chemotaxis to inflamed sites in the brain." (PMID 30004409, 2018). "CCR6-knockout mice are protected against brain damage from stroke." (PMID 35453602, 2022). "Interestingly, CCR6 expressed by tissue resident γδ T cells has also been shown to play an important role in stroke and subsequent brain ischemia." (PMID 34829761, 2021). "Genetic deficiency in Ccr6 significantly diminished the infiltration of γδ T cells, highlighting the important role that chemokine (C-C motif) ligand 20 (CCL20)/CCR6 axis plays for γδ T cell migration in stroke." (PMID 33868300, 2021). "Immune-mediated tissue damage occurs in the first few days of suffering a stroke and is mainly attributed to brain-infiltrating, IL-17 releasing, γδ T cells which are largely positive for the chemokine receptor CCR6 as they trigger a highly conserved immune reaction." (PMID 30004409, 2018).
chronic obstructive pulmonary disease (3 papers, 2017 to 2023). A chronic and progressive lung disorder characterized by the loss of elasticity of the bronchial tree and the air sacs, destruction of the air sacs wall, thickening of the bronchial wall, and mucous accumulation in the bronchial tree. "In other respiratory diseases such as chronic obstructive pulmonary disease (COPD), the increased presence of DCs in the lungs correlated with the upregulation of CCR6 on DCs and an increase of the CCR6 ligand (CCL20) in the airways." (PMID 28640917, 2017). "Moreover, in chronic obstructive pulmonary disease (COPD), a disease characterized by chronic airway inflammation, the CCR6/CCL20 axis provides a possible mechanism for the accumulation of dendritic cells in the lungs of patients with COPD." (PMID 37092451, 2023).
Cirrhosis (3 papers, 2010 to 2025). A chronic disorder of the liver in which liver tissue becomes scarred and is partially replaced by regenerative nodules and fibrotic tissue resulting in loss of liver function. "CCL20/CCR6 mRNA and protein expressions in PCA were compared to several clinicopathological factors such as TNM stages, age, lymphatic and vascular invasion or pre-existing conditions like cirrhosis or fibrosis." (PMID 20459729, 2010).
co-infection (3 papers, 2015 to 2024). "Majority of the MAIT cells in HCs showed a significant increase in CCR6 expression as compared to HIV/TB co-infections." (PMID 25894562, 2015). "In addition, the qPCR analysis showed the chemokines ccl4, ccr6, ccr9, and cd5 were significantly down-regulated during lice infection alone vs pre-infection, and comparable with that of co-infection." (PMID 35046944, 2021).
colorectal tumor (3 papers, 2011 to 2021). "Notably, we identified that these accumulating GFP+ Treg-cells within colorectal tumor expressed CCR6, the Treg-cell homing receptor." (PMID 21559338, 2011). "In order to confirm whether CCR6 was required for migration of Treg-cells to tumor sites, we grafted mouse colorectal tumor cell line CMT93 into CCR6 −/− mice." (PMID 21559338, 2011). "Furthermore, in immunosuppressed xenograft mouse models, where many stromal effects should be abrogated, it has been shown that blockade of CCL20-CCR6 interactions decreases colorectal tumor growth, and that overexpression of CCR6 in the cancer cells promotes metastases." (PMID 34853656, 2021). "Expression of CCR6, the receptor for CCL20 in human colorectal tumors and adjacent uninvolved colon was measured by semi quantitative RT-PCR." (PMID 24866282, 2014). "In addition, we digested colorectal tumor from mice treated with MNU and H. pylori, and determined CCR6 expression of tumor-infiltrating Treg-cells by Flow cytomery." (PMID 21559338, 2011).
depression (3 papers, 2021 to 2023). "Direct evidence of CCR6 involvement in depression-like behavior came from CCR6−/− mice showing an anhedonic phenotype as indicated by reduced preference for saccharin compared to WT animals." (PMID 33921690, 2021).
eosinophilia (3 papers, 2011 to 2021). "It is also reported that the CCL20/CCR6 system plays a pivotal role in allergic airway responses such as airway resistance, airway eosinophilia, and production of IL-5 and IgE." (PMID 22013453, 2011). "First, an experimental model of OVA-induced AHR, airway eosinophilia, and type 2 cytokine production was used to monitor the activities of CCL20 and CCR6+ Treg cells." (PMID 34497608, 2021). "It has also been reported that the CCL20/CCR6 system may play a pivotal role in allergic airway responses such as AHR, airway eosinophilia, and production of IL-5 and IgE." (PMID 28628664, 2017).
fibrosis (3 papers, 2010 to 2024). the formation of excess fibrous connective tissue in an organ or tissue in a reparative or reactive process. "To investigate the role of CCR6 during fibrogenesis in early phases of fibrosis and in a well-established fibrosis model, we assessed fibrosis in wt and Ccr6-/- animals by injecting mice with CCl4 during 2 and 4 weeks." (PMID 26691857, 2015).
food allergy (3 papers, 2018 to 2025). Gastrointestinal disturbances, skin eruptions, or shock due to allergic reactions to allergens in food. "TH2 cytokine driven experimental food allergy was induced in a mouse model to evaluate both CCR6+/+ and CCR6−/− cohorts, taking allergic diarrhea as a pre-clinical parameter." (PMID 30453514, 2018). "It will be important to characterize and validate Ara h 1, 3, and 6 dominant epitope by this CD154 epitope mapping approach given that a relatively high percentage of Ara h 1, 3, and 6-specific CD4 T cell express CCR6, which is potentially a producer of IL-17 as observed in other food allergy." (PMID 29988522, 2018).
Granuloma (3 papers, 2019 to 2022). A compact, organized collection of mature mononuclear phagocytes, which may be but is not necessarily accompanied by accessory features such as necrosis. "Additionally, a significantly higher (P < 0.0001) percentage of Th17 responses (CCR6+CD4+ T cells) was observed in the granulomas of the cART/2-week group." (PMID 34855621, 2022). "The density of several transcripts including Ccr6, Cd19, and Il12, and to a lesser degree Cd3e, Cxcr3, and Cd8b mRNA was increased in the lymphoid in relation to the epithelioid areas after a supervised annotation of the lymphoid and the epithelioid areas of the granulomas based on H&E staining." (PMID 31015452, 2019).
idiopathic pulmonary fibrosis (3 papers, 2016 to 2024). Idiopathic pulmonary fibrosis (IPF) is a nonneoplastic pulmonary disease that is characterized by the formation of scar tissue within the lungs in the absence of any known cause. "Finally, radiation-induced pulmonary fibrosis leads to Ccr6 expression in the lungs of mice and may be involved in fibrogenesis." (PMID 39768150, 2024). "IL-17A, a well-established fibrogenic inducer in murine pulmonary fibrosis models and IPF samples, activates CCR6+ Th17 lymphocytes, responding to CCL20 levels." (PMID 39768150, 2024). "Despite the fact that these patients suffered from lung fibrosis, the fibroblast lines isolated from these lungs showed no CCR6 expression." (PMID 38334630, 2024).
lung diseases (3 papers, 2021 to 2024). "Next, we determined the mRNA levels of CCR6 in cultured human primary fibroblast lines isolated from the lungs of patients with varying pulmonary diseases." (PMID 38334630, 2024). "In the blood of cystic fibrosis patients, low circulating CCR6+ ILC2s correlate with increased disease severity and advanced pulmonary disease." (PMID 39768150, 2024). "Further verification was done by qPCR as we tested five differential peak-related genes (Rras2, Ttll12, Ccr3, Ccr6 and Trps1) with known contributions to lung diseases." (PMID 33902609, 2021). "In zones of active lung disease, IPF samples showed an increased number of CCR6+ and IL-17A+ expressing cells compared with histologically normal lung areas." (PMID 39768150, 2024). "Despite data linking CCR6 to important lung diseases, there are currently no publications describing CCR6 antagonists or neutralizing reagents for clinical use in humans." (PMID 39768150, 2024).
oral cancer (3 papers, 2018 to 2020). "A considerable part of the CD39+ Treg in the tumor expressed CCR6 and interestingly for this context, CCR6+ regulatory T cells have been associated with superior suppressive activity in oral cancer." (PMID 30651930, 2018). "In this study, we also determined the expression levels of CCR6 and CCR8 in oral cancer." (PMID 32641093, 2020).
periodontitis (3 papers, 2017 to 2024). An acute or chronic inflammatory process that affects the tissues that surround and support the teeth. "We found that exFoxp3T cells in periodontitis-induced mice are characterized by a higher expression of RANKL and CCR6 than GFP–YFP– T cells (conventional T cells)." (PMID 29453398, 2018). "P. gingivalis-Th17 cell migration aggravates periodontitis progression, indicating that inhibiting the CCL20/CCR6 axis could prevent periodontitis from developing." (PMID 39131163, 2024). "Accordingly, ILC3s of periodontal tissues from control animals (i.e., without periodontitis) display more marked CCR6 expression either without or with IL-1β/IL-23 treatment compared to those of periodontitis model; however, the effect was more marked for cytokines-treated ILC3s." (PMID 28861078, 2017).
pneumonia (3 papers, 2020 to 2024). An acute, acute and chronic, or chronic inflammation focally or diffusely affecting the lung parenchyma, caused by an infection in one or both of the lungs (by bacteria, viruses, fungi, or mycoplasma.). "Statistical assessment of patients with acute myeloid leukemia (AML) and myelodysplastic syndromes (MDS) treated with ICIs revealed enrichment of IFNγ+ IL-17- CD8+ T and CXCR3+ CCR6+ Th17/Th1 cells in BALF in the group developing pneumonia." (PMID 38426102, 2024). "Differential expression of IL-17 in BAL IFNγ+ IL-17- CD8+ T and CXCR3+ CCR6+ Th17/Th1 cells was noted in BAL fluid of patients with ICI-Pneumonitis compared to patients with pneumonia; however, larger studies are needed to confirm these findings." (PMID 34675810, 2021). "Some studies have reported that hyperactivation of CCR4+ CCR6+ Th17 and high cytotoxicity of CD8+ T lymphocytes existed in patients with pneumonia." (PMID 32669467, 2020).
prostate tumors (3 papers, 2009 to 2025). "To further study the expression pattern of CCL20 and CCR6 in prostate tumors, we stained additional specimens from 44 primary tumors." (PMID 19340288, 2009).
renal carcinoma (3 papers, 2016 to 2023). A carcinoma arising from the epithelium of the renal parenchyma or the renal pelvis. "Moreover, T regulatory (Treg) cells, infiltrating renal cancer, express high level of CCR6 and its ligand CCL20 is expressed on tumor cells, representing a homing mechanism for Treg that favours the tumor immune escape." (PMID 27322553, 2016).
thyroid tumor (3 papers, 2018 to 2025). A benign or malignant neoplasm affecting the thyroid gland. "TNF-α stimulation was reported to increase CCR6+ cells in thyroid tumor lines TPC-1 and BCPAP." (PMID 40150133, 2025).
uveitis (3 papers, 2018 to 2024). An inflammatory process affecting a part of or the entire uvea. "Since manual as well as unsupervised gating methods linked CCR6-expressing T helper cells to uveitis biology and treatment use, we suggest this T cell family should be a central subject of such studies." (PMID 30429855, 2018). "Within the CD4+ TM subset, uveitis patients showed a significant increase in the proportion of CCR6+CXCR3− cells (Th17) and a decreased proportion of CCR6−CXCR3+ (Th1) cells (p = 0.02 and p = 0.04 respectively)." (PMID 30429855, 2018). "In line with this, we observed an increase of (CCR6+CXCR3−) Th17 cells within CD4 TM cells that was noticeable for all uveitis types." (PMID 30429855, 2018). "Notably, our previous induced uveitis rodent studies demonstrated SOCS1-KIR mediated decreases in the chemokines CCL2, CCL20 and CXCL9, in addition to the chemokine receptors CCR2, CCR4, CCR6 and CXCR35,25." (PMID 35505065, 2022). "Importantly, regardless of the uveitis subtype, patients that eventually required IMT in the course of the study follow-up exhibited increased CCR6+ T cell abundance before commencing therapy." (PMID 30429855, 2018).
acute myocardial infarction (2 papers, 2021 to 2024). Necrosis of the myocardium, as a result of interruption of the blood supply to the area. "This study demonstrates that CCR6-dependent (bone marrow) cells exert a protective role in myocardial infarction and subsequent ischemia-reperfusion injury, supporting the notion that augmenting CCR6-dependent immune mechanisms represents an interesting therapeutic target." (PMID 34829761, 2021). "Therefore, to gain more insight into the role of the CCR6 in acute myocardial infarction, we have studied cardiac injury after transient ligation of the left anterior descending coronary artery followed by reperfusion in Ccr6−/− mice and their respective C57Bl/6 wild-type controls." (PMID 34829761, 2021).
adenoma (2 papers, 2014 to 2024). A neoplasm arising from the epithelium. "Our data clearly show that CCR6 is an important factor in the sporadic development of intestinal adenomas as its absence results in a marked decrease in adenomas by 2 measures at 2 time points." (PMID 24866282, 2014). "We also made interesting initial observations on the potential mechanism of CCR6 in adenoma development." (PMID 24866282, 2014). "The CD4+CCR6+ Th17 cell proportion decreased in CRC when compared with the healthy control group (23.1 vs. 11.2, P = 0.0279) or adenoma grade I (24.3 vs. 11.2, P = 0.0163) or even adenoma grade II (21.7 vs. 11.2, P = 0.0042)." (PMID 38343544, 2024). "Counter-intuitively, in the absence of CCR6, there was a trend toward increased T cell infiltration into both adenomas and non-tumor epithelium." (PMID 24866282, 2014). "We further noted that APCMIN/+ mice without functional CCR6 appeared to live longer and to be healthy at a later time point due to the decreased adenoma development." (PMID 24866282, 2014).
B cell lymphoma (2 papers, 2018 to 2021). "Each chemokine was tested for its ability to chemoattract L1.2 mouse B cell lymphoma cells expressing the cognate mouse receptors Ccr6, Ccr7, and Ccr1, respectively, in the presence of increasing doses of DOPS or DOPC liposomes." (PMID 34038417, 2021).